BCL2 (BCL2 apoptosis regulator)
Diseases named in the same sentence as BCL2 in open-access papers (continued):
Sharing a sentence is not in itself a finding about the gene and the disease.
cancer (continued). "Bcl-2, for which the gene product is known to have a role in apoptosis reduction, was one of the direct target genes of miR-181a and inhibited mitochondrial metabolism and ADM-induced apoptosis in cancer cells." (PMID 29849870, 2018). "Moreover, binding of Bcl-2 to Bax was abrogated in the presence of IDF-11774 and bafilomycin A1, leading to apoptosis in cancer cells." (PMID 30420612, 2018). "Similarly, an ethyl acetate extract derived from leaves of A. muricata induced apoptosis in lung A549 cancer cells through elevating ROS formation, followed by attenuation of MMP via upregulation of Bax and downregulation of Bcl-2." (PMID 30151067, 2018). "Interestingly, new specific pathway inhibitors, e.g. Bcl-2 or BCRi, with excellent response rates in refractory CLL affect pathways promoting growth of cancer cells under severe hypoxia." (PMID 29884457, 2018). "Furthermore, encouraging preclinical studies of BH3 mimetics that target other BCL-2 pro-survival members, particularly MCL-1, offer promise for cancers resistant to venetoclax." (PMID 29099483, 2018). "Given that venetoclax selectively inhibits BCL-2, this compound should be effective in cancer cells that express BCL-2; however, this does not always occur." (PMID 30671383, 2018). "Recent studies have revealed that adiponectin decreases Bcl‐2 expression 4; however, the molecular mechanism by which adiponectin suppresses Bcl‐2 expression in cancer cells is not well defined." (PMID 30524947, 2018). "MAT2A overexpression enhances cancer cell growth and survival, as there is a positive feedforward loop between MAT2A and polyamines and MAT2A protein positively regulates B-Cell CLL/lymphoma 2 (BCL-2) expression." (PMID 29108270, 2017). "It was suggested the BCL-2 expression is regulated by ATF5 in cancer cells but not in non-transformed cells." (PMID 28785242, 2017). "Unlike BCL-2 inhibition, which failed to sensitize cancer cells to PI3K/mTOR treatment, BCL-XL inhibition increased cell killing by GNE-493 in most of the PDX models." (PMID 28848242, 2017). "BCL-2/BAX ratio also serves as a predictor of drug efficacy and cancer invasiveness." (PMID 28235409, 2017). "These molecules mimic the BH3 domain of Bad, a sensitizer BH3-only protein thereby disrupting Bcl-2/Bim complexes and releasing Bim from the hydrophobic cleft of Bcl-2, which then results in Bax/Bak-mediated apoptosis in cancer cells but not in healthy cells." (PMID 29340082, 2017). "Consequently, molecules possessing only the BH3 domain of BCL-2 proteins (termed BH3 mimetics), have received significant attention as potentially useful cancer therapeutic agents either alone or in combination with other drugs." (PMID 28055968, 2017). "The direct relationship between Nrf2 and Bcl-2 expression was identified, in which Nrf2 directly bound to an ARE in the promoter region of Bcl-2 gene to upregulate Bcl-2 expression and increase the survival of cancer cells." (PMID 28032588, 2017). "This important finding and the selective impairment of the interaction between La and Bcl2 and CCND1 mRNAs, suggests that the compounds might target La-supported cancer cell promoting processes." (PMID 28291789, 2017). "Antp-LP4 peptide prevented the anti-apoptotic effects of HK, Bcl-2, or Bcl-xL and induced cell death in several cancer cell lines, while being less effective in non-cancerous cells." (PMID 28824871, 2017). "Among many oncogenes, VEGFA, BCL2 and KRAS are overexpressed in many types of cancer cells." (PMID 28102286, 2017). "Combined inhibition of BCL-2, BCL-XL and MCL-1 through mechanism-guided combination therapy will provide the most effective and a potentially universal therapeutic strategy to eradicate cancer cells through apoptotic induction." (PMID 28714472, 2017).
cancer (continued). "The role of BCL2 expression in cancer development and progression is complex and still not fully understood." (PMID 28396899, 2017). "When it comes to the experimental results in Hela cells, the Bax/Bcl2 ratio reached 1.003, which suggested that U1 snRNA over-expression had not induced apoptosis in cancer cells." (PMID 29348872, 2017). "Introducing VDAC1’s N-terminal into cells was shown to inhibit both Bcl-2’s and Bcl-XL’s anti-apoptotic function, illustrating that VDAC1 could be a target for anti-cancer drugs." (PMID 28516063, 2017). "BDA-366 also impaired IP3R/Bcl-2 complex formation and raised cytosolic Ca2+ levels, although further work is needed to determine the contribution of Ca2+ signaling to BDA-366-induced cell death in cancer cells." (PMID 28516063, 2017). "Further gene transcript paneling of genes related to cancer activity in cells also showed no changes with both nuclear factor kappa‐light‐chain‐enhancer of activated B cells (NF‐κβ), and B‐cell lymphoma 2 (BCL‐2) expression." (PMID 28396842, 2017). "In addition, inhibition of miR-7641 boosted doxorubicin-mediated apoptosis of cancer cells via upregulation of apoptotic molecules Caspase 9 (CAS9) and poly ADP ribose polymerase (PARP) and downregulation of anti-apoptotic molecule BCL2." (PMID 28827731, 2017). "This is consistent that the opposite correlation between both Bcl-2 inhibitors is valid for Bcl-2-dependent cancer cells, but not for cancer cells dependent on other Bcl-2-family members, like Bfl-1." (PMID 29340082, 2017). "Some scorpion venoms target caspases, mitochondria, Bcl-2, and BAX and may thereby contribute to cancer treatment." (PMID 30873475, 2017). "This reciprocal sensitivity between venetoclax and BIRD-2 appeared to count for Bcl-2-dependent cancer cells, but not for Bfl-1-dependent cancer cells, as the Bfl-1-dependent cancer cell line PFEIFFER was relatively resistant to both venetoclax and BIRD-2." (PMID 29340082, 2017). "Yet, a more detailed analysis directly comparing and correlating the response of a larger set of different Bcl-2-dependent DLBCL cancer cells to BIRD-2 versus venetoclax has not been performed." (PMID 29340082, 2017). "While ABT263 efficiently inhibits Bcl-xL, Bcl-2 and Bcl-w, it fails to bind Mcl-1, which is also commonly up regulated in cancer cells." (PMID 28418907, 2017). "Yet the notion why BCL2 overexpression can rescue primary mouse B cells and human cancer cells from apoptosis in vitro but fails to restore murine B cell development in vivo remains unexplained." (PMID 29167438, 2017). "Additional roles of this region in VDAC1 oligomerization and regulation of apoptosis are presented below (see VDAC1 Homo-Oligomer Forming the Cyto c Release Pathway) and as the binding site for HK, Bcl-2, and Bcl-xL (see VDAC1-Based Peptides As Potential Anti-Cancer Therapy)." (PMID 28824871, 2017). "Down-regulation of oncogenic miR-20a-5p and further regulating several important cancer genes (such as PTEN and BCL2) may provide a potential MOA for therapeutic effect of metformin in breast cencer." (PMID 27329603, 2016). "The inhibition of anti-autophagic proteins, such as Bcl2, PKCδ, and tissue transglutaminase 2 (TG2), may lead to autophagic cell death in some apoptosis-resistant cancers." (PMID 27658240, 2016). "In addition, mRNA data of hematopoietic and lymphoid tissue cancer cell lines of the Novartis and Broad Institute Cancer Cell Line Encyclopedia were queried for TRPM2 and Bcl-2 mRNA abundance." (PMID 26839633, 2016). "In the present study, using our pH-sensitive liposomal nanocarrier system we successfully delivered two therapeutic agents PTX and Bcl-2 siRNA, simultaneously into cancer cells in time dependant manner with no toxicity." (PMID 27786239, 2016).
cancer (continued). "Moreover, inhibitors of BET binding can disrupt the growth of cancer cells and this phenomenon has been attributed to the sensitivity of super-enhancers, driving oncogenes such as MYC and BCL2, to BET disruption." (PMID 27097319, 2016). "In cancer, they can upregulate transcription of key oncogenes such as cMYC, IRF4, and BCL-2." (PMID 27903272, 2016). "Those pathways specifically altered in primary tumors were associated with an abnormally increased expression of genes that are involved in focal adhesion (e.g., PRKCA, CRK, and BCL2), PI3K-Akt signaling (e.g., PHLPP2, PRKCA, PPP2R3A and KIT) and cancer pathways (e.g., COL4A5, LAMC1 and BCL2L1)." (PMID 27662660, 2016). "Moreover, inhibitors of BET binding can disrupt the growth of cancer cells and this phenomenon has been attributed to the acute sensitivity to BET disruption of super-enhancers at oncogenes such as MYC and BCL2." (PMID 27097319, 2016). "For example, expression of EGFR was decreased in the eight cancer cell lines after transfection of siSp1, siSp3 and siSp4 and expression of all of gene products (EGFR, survivin, bcl-2 and VEGF) were decreased in cells transfected with siSp3 and siSp4 but variable responses were observed for siSp1." (PMID 26967243, 2016). "Taken together, these results suggest that GA exerted anti-cancer effect specifically in TKIR cells by inhibiting Src-mediated Stat3 phosphorylation, downregulating Stat3 target genes, especially Bcl2 and cyclin D, hence inducing apoptosis and cell cycle arrest." (PMID 27419630, 2016). "Bcl-2 dependence in NB, like other cancers, is not due to an overabundance of Bcl-2 in the cell compared to other anti-apoptotic members, but due to the functional dependence on Bcl-2 to bind to and sequester activated Bim." (PMID 26874859, 2016). "Further studies will be needed to explore the mechanistic insights of Bcl-2's inhibition on PKC412's activity, and if this could also be seen in other cancer cells." (PMID 27780925, 2016). "miR-16 has an important role in regulating apoptosis in different cancer types including lung, breast, liver, glioblastoma, and squamous cell carcinoma through targeting FEAT/METTL13, RPS6KB1, IGF1R, CCND1, BCL2, RECK, and/or SOX6." (PMID 27128908, 2016). "Moreover, suppression of mTORC1-dependent translation has been shown to reduce the levels of MCL-1 and sensitize various cancer cells, including ABT-199 resistant DLBCL, to BCL-2 antagonists." (PMID 26460954, 2015). "A synthetic class of BH3 mimetics that has been developed recently shows interesting results regarding their capacity to radiosensitize cancer cells, including ABT-737, a molecule with high affinity for Bcl-2 and Bcl-xL, and its analogue the clinically more favorable, ABT-263." (PMID 26223311, 2015). "There are several potential mechanisms for iNOS inhibition affecting the resistance of cancer cells to apoptosis, which include interference with PI3K/AKT-mediated overexpression of surviving, or release of caspase activation, or stabilization of Bcl-2." (PMID 26196284, 2015). "From a mechanistic point of view, we identified down-regulation of Usp9X as well as Bag3 followed by enhanced Mcl-1-degradation as one of the driving mechanisms subjacent to the profound anti-cancer activity inherent to a combined inhibition of ERK signaling and Bcl-2/Bcl-xL." (PMID 26474387, 2015).
cancer (continued). "Activation of the STAT3 signaling pathway can upregulate the target genes, including Bcl-X, Bcl-2, Cyclin D1, vascular endothelial growth factors (VEGF), Fas, Survivin and other factors, allowing cancer cells to escape apoptosis and inducing cell proliferation." (PMID 25895131, 2015). "The expression levels of Bcl-2 and Mcl-1 varied among the nine cancer cell lines, suggesting that it was not contributing to TRAIL resistance." (PMID 26506422, 2015). "SAMe and MTA treatment lowered Bcl-2 expression, an effect that has not been previously reported and likely also contribute to their pro-apoptotic effect in these cancer cell lines." (PMID 26416353, 2015). "NF-κB pathway plays an important role in regulating cancer cells proliferation, anti-apoptosis, invasion and metastasis and angiogenesis, through modulating series of functional genes expression and activity, including IL1A, CCND1, MYC, Bcl-2, MMP9 and VEGF." (PMID 26429874, 2015). "This chimera, containing HER2-Bcl2 siRNA, targets HER2 expressing cancer cells specifically and initiates the downregulation of the Bcl2 gene, thus opening a new combinational strategy against cancer." (PMID 28536411, 2015). "In the current study, we investigated the mechanism of curcumin-induced apoptosis in upper aerodigestive tract (lung and head and neck) cancer cell lines and showed that curcumin inhibited survival signals (p-AKT and Bcl-2), the reversal of which protected cells." (PMID 25910231, 2015). "In addition, phosphorylation of Bcl-2 at Serine 87 via JNK signaling pathway promotes apoptosis in fibroblast and cancer cells when both cells are at the mitotic arrest." (PMID 25826088, 2015). "Overexpression of anti-apoptotic Bcl-2 and Bcl-xL proteins rendered HCC cells more resistant to chemotherapeutic agents, such as staurosporine, Dox, and paclitaxel, in human HCC whereas reduced level of Bcl-2 sensitized cancer cells to these agents." (PMID 26247632, 2015). "Supplementation with the NM has beneficial effects in modulating cancer markers of proliferation (Ki67), invasion/metastasis (MMP-2 and -9), angiogenesis (VEGF), apoptosis (TUNEL and Bcl-2) and inflammation (COX-2 and iNOS), as well as the general cancer marker GSTπ." (PMID 25574189, 2015). "Our observations show that for an effective elimination of cancerous cells simultaneous down-regulation of Bcl2 following by over expression of Bax is a preferred approach and persistent expression of Bcl2 and IAP proteins can be a mechanism by which cancer cells exhibit resistance to chemotherapy." (PMID 26074734, 2015). "In other words, postmenopausal patients with Bcl-2-negative and hormone receptor-negative (or triple-negative) cancers exhibited quite favorable clinical outcome even without adjuvant chemotherapy." (PMID 26472348, 2015). "Further, we also found the down regulation of anti-apoptotic molecules BCL-2, Bcl-xL, cIAP2, XIAP, Axin2 and Survivin in the AKAP4-depleted CRC cells indicating that AKAP4 may be potential therapeutic target in cancer management." (PMID 26590805, 2015). "We found that the BECLIN 1-positive cancers associated with the patients deceased during the study were indeed negative for vacuolar LC3 staining and highly expressing BCL-2." (PMID 25136588, 2014). "Unlike other oncogenes that increased cell proliferation, Bcl-2 inhibited programmed cell death and affected the apoptotic pathway, which are critical for cancer development." (PMID 24387269, 2014). "In other reports it was shown that high expression of bcl-2 has an adverse effect on the occurrence of complete remission, but only in the cancer group TP 53 negative." (PMID 25018782, 2014).
cancer (continued). "In addition, NF-κB controls the critical genes including COX-2, Bcl-2, and genes required for invasion and angiogenesis such as MMP9 and VEGF in the early and late stages of aggressive cancer." (PMID 24845412, 2014). "However, miR-497 can also attenuate the malignancy of cancers by regulating other targets, such as TARBP2, DICER, BCL2, CCND1, CCNE1, CDC25A, CCND3, CDK4." (PMID 24667580, 2014). "We used degradable, pH-sensitive, comb-like [P(EAA-co-BMA)-b-PNASI-g-P(HMA-co-TMAEMA)] polymer to condense anti-Bcl-2 siRNA into “smart” particles, which proved to shuttle their cargo past the endosomal membrane and into the cytoplasm of HeLa and UM-SCC-17B cancer cells." (PMID 25229941, 2014). "Once Bcl-2 and Bcl-xL are neutralized and weakened, active Bax will transpose to mitocondria and stimulate mitochondrial outer membrane permeabilization (MOMP) to release pro-apoptotic molecules into proteins, thus inducing apoptosis of cancer cells." (PMID 25100434, 2014). "Similarly, “smart” anti-Bcl-2 particles inhibited Bcl-2 mRNA levels by 30%, 40%, and 20% upon incubation with UM-SCC-17B cancer cells for 48, 72, and 96 h, respectively." (PMID 25229941, 2014). "Additionally, inhibition of ERK1/2 activation downregulated the expressions of Bcl-2 and Bcl-xl, and ERK1/2/Bcl-2 signaling is believed to be a potential therapeutic target for cancer cells." (PMID 25342459, 2014). "We investigated whether the inhibition of survivin, Bcl-2 and Mcl-1 by honokiol could sensitize MDR cancer cells to conventional chemotherapy such as palictaxel." (PMID 24586249, 2014). "Most authors reported activation of apoptosis in cancer cells under the effect of Helicobacter pylori, with activation of its mitochondrial pathway and increased expression of BID and Bax, or antiapoptotic Bcl-2." (PMID 24741635, 2014). "Bcl-2: This gene is not expressed in the normal prostate, but is commonly expressed in prostate and other primary cancers." (PMID 24282788, 2013). "Importantly, C/EBPα induces BCL2 and FLIP gene expression in cooperation with NF-κB p50, allowing cancer cells to escape apoptosis." (PMID 24359396, 2013). "In addition, miRNA-29-a is well known of oncosuppressor miRNA, which is frequently lost or down-regulated in cancer so that target oncoproteins like CDK6, MCL1, or BCL-2 can be upregulated." (PMID 24521303, 2013). "A lower expression of Bcl-2 and a higher expression of IGF-1R in unclassified tumors compared to ER/PR + HER2- were thus suggested to be partly involved in the reported worse prognosis of unclassified type cancer than ER/PR + HER2-." (PMID 24245483, 2013). "By contrast, in maunka-treated cancer cells, no decrease in Bcl-2 expression was observed at 24 hrs; however, by 72 hrs, there was >50% reduction in Bcl-2 levels." (PMID 23409104, 2013). "The decreased expression of death receptors TRAIL-R1 and TRAIL-R2 and antiapoptotic proteins (Bid, Bax, Bak, Smac/DIABLO) or increased expression of antiapoptotic proteins (FLIP, Bcl-2, Bcl-xL, Mcl-1, Akt, IAP-1, IAP-2, XIAP, survivin) in cancer cells were involved in TRAIL-resistance." (PMID 23573148, 2013). "Since the mechanisms by which MDA-7/IL-24 suppresses Bcl-2 expression and facilitates cancer cell apoptosis have not been clarified." (PMID 22629368, 2012).